HK2 (hexokinase 2)
Diseases named in the same sentence as HK2 in open-access papers (continued):
Sharing a sentence is not in itself a finding about the gene and the disease.
gastric cancer (continued). "In conclusion, our findings show that SALL4 induces glycolysis via the upregulation of HK-2, thus promoting the proliferation, migration and invasion of gastric cancer cells." (PMID 32489324, 2020). "HK-2 knockdown abrogated the promotion of glycolysis by SALL4 in gastric cancer cells, indicating that HK-2 acts as a downstream effector of SALL4." (PMID 32489324, 2020). "Increased levels or activities of three rate-limiting enzymes involved in glycolysis, including HK-2, accelerates gastric cancer progression and leads to poor prognosis in cancer patients." (PMID 32489324, 2020). "WTAP accelerates the Warburg effect of gastric cancer by regulating HK2 stability." (PMID 39744575, 2025). "In addition, the circadian rhythm of the PER1/HK2 axis was shown to be significantly correlated with trastuzumab resistance in gastric cancer." (PMID 40415238, 2025). "Additionally, recent translational research has underscored the importance of HK2 in liver cancer and gastric cancer treatment, revealing its ability to induce resistance to targeted drugs." (PMID 41245305, 2025). "However, the TRIM25-mediated ubiquitination of HK2 has been less studied, especially in gastric cancer." (PMID 40796546, 2025). "Both in vivo and in vitro experiments showed that licochalcone A could reduce HK2 expression, inhibit glucose consumption and lactic acid production in gastric cancer cells, and hinder cell survival and proliferation." (PMID 39991762, 2025). "It has been found that celastrol could inhibit the expression and activity of HK2 in gastric cancer cells, thus inhibiting their glycolysis." (PMID 39991762, 2025). "Moreover, HK2 overexpression significantly reversed the inhibitory effect on the proliferation of gastric cancer cells induced by NLRP12 knockdown." (PMID 40796546, 2025). "In addition, G6PD promotes gastric cancer cell proliferation and metastasis through mechanisms mediated by NF-kB and hexokinase 2 (HK2)." (PMID 41374996, 2025). "In addition, we found that SMAD4 was low-expressed in gastric cancer tissues and high-expressed in the corresponding adjacent normal tissues and GLUT1 and HK2, key proteins for glycolysis, are relatively more highly expressed in gastric cancer tissues." (PMID 38686046, 2024). "While HK-2 is an important molecular target in gastric cancer because it is involved in regulating accelerated glucose uptake during aerobic glycolysis, and these cells rely preferentially on aerobic glycolysis for energy generation rather than on mitochondrial respiration." (PMID 36985571, 2023). "In gastric cancer tissues, the expression of HK2 and PFK is decreased when STAT3 is knocked down." (PMID 37599427, 2023). "WTAP promoted the proliferative ability of gastric cancer cells and increased their glycolytic capacity (glucose uptake, lactate production, and extracellular acidification rate) by stabilizing the hexokinase-2 (HK2) mRNA by binding to its 3ʹ-UTR m6A site." (PMID 36207306, 2022). "Through research on stomach cancer, it was discovered that baicalin inhibits the expression of three important glycolysis enzymes, HK2, LDHA, and PDK, reducing the rate of glycolysis and reversing the hypoxia-induced sensitivity of AGS cells to pentafluorouracil." (PMID 36339566, 2022). "The expression of HK2 is promoted by lncRNA Ftx in gastric cancer cells." (PMID 36438836, 2022). "CircBFAR promotes glycolysis in gastric cancer cells by targeting the miR-513 a-3p/HK2 axis." (PMID 36438836, 2022). "WTAP enhanced the Warburg effect via regulation of HK2 stability in gastric cancer." (PMID 36003776, 2022). "Previous reports indicated that the upregulation of STAT3/HK2 contributed to the activation of dendritic cells by leptin-induced glycolytic metabolism, and circular RNA circCUL3 eliciting the Warburg effect of gastric cancer." (PMID 36431990, 2022).
gastric cancer (continued). "Inhibition of the HK2 expression could effectively inhibit the glucose uptake, lactate production, proliferation, and migration of gastric cancer cell lines." (PMID 33718248, 2021). "However, when analyzing the survival curve (the data from Kaplan Meier-plotter) for gastric cancer patients, it was found that the patients exhibiting high HK2 expression had a longer survival time than those with low HK2 expression." (PMID 33718248, 2021). "These outcomes suggested that HK2 played an important role in the development of gastric cancer and GCMSCs could promote glycolysis in gastric cancer cells." (PMID 33718248, 2021). "Furthermore, we demonstrated that HGF derived from GCMSCs promoted the proliferation and metastasis of gastric cancer cells by upregulating HK2." (PMID 33718248, 2021). "These outcomes indicated that GCMSCs could regulate the proliferation, migration, and metabolism of gastric cancer cells by upregulating HK2 in vitro." (PMID 33718248, 2021). "By analyzing patient survival curves, the expression of HK2 in cancer tissues may become an indicator for 5-FU treatment in gastric cancer chemotherapy." (PMID 33718248, 2021). "Our results suggest that SALL4 could promote gastric cancer progression through HK-2-mediated glycolysis, which represents a new mechanism for the oncogenic roles of SALL4 in cancer." (PMID 32489324, 2020). "In this study, we found that SALL4 could also regulate the transcription of HK-2, thereby promoting glycolysis and gastric cancer progression." (PMID 32489324, 2020). "The gastric cancer cells with high levels of SALL4 seem to also have increased expression of HK-2." (PMID 32489324, 2020). "PVT1 could interact with FOXM1 directly and increase its protein expression in gastric cancer and increased glucose uptake, lactate production, and the expression of HK2 in osteosarcoma cancer." (PMID 30083911, 2019). "Therefore, HK2 inhibition is crucial for exploring targeted therapies for gastric cancer." (PMID 40796546, 2025). "In gastric cancer, mesenchymal stem cells (GCMSCs) have been implicated in inducing chemoresistance to oxaliplatin (OXA) and Paclitaxel (PTX) through the regulation of hexokinase 2 (HK2), possibly involving the TNF-α/p38 signaling pathway, with B7-H3 silencing mitigating this effect." (PMID 40214484, 2025). "Because the most prevalent autophagy-targeting signal in mammals is cargo K63-linked ubiquitination, we examined the level of HK2 ubiquitination in gastric cancer cells to further investigate whether the mechanism by which NLRP12 increases the expression of HK2 protein is related to ubiquitination." (PMID 40796546, 2025). "Additionally, PDLIM1 modulates the Warburg effect—a phenomenon where cancer cells exhibit increased glucose uptake and lactate production, critical for the tumor microenvironment—by interacting with HK2 and regulating the Wnt/β-catenin pathway in gastric cancer." (PMID 39548074, 2024). "Moreover, HK2 was reported to be facilitate for cell proliferation and tumor formation, such as cervical cancer, gallbladder cancer, diffuse large B-cell lymphoma, gastric cancer, hepatocarcinoma and so on." (PMID 35953860, 2022). "Hence, we hypothesized that GCMSCs could upregulate the expression of HK2 in gastric cancer cells by secreting HGF." (PMID 33718248, 2021). "Therefore, SALL4 may maintain the malignant phenotypes of gastric cancer cells by regulating HK-2-mediated glycolysis." (PMID 32489324, 2020). "Considering that HK-2 is the first rate-limiting enzyme of glycolysis and it showed the most significant change after SALL4 knockdown and overexpression in gastric cancer cells, we hypothesized that SALL4 might promote glycolysis through the regulation of HK-2 in gastric cancer cells." (PMID 32489324, 2020).
gastric cancer (continued). "In gastric cancer cells, PDLIM1 (PDZ and LIM domain protein 1) interacted with HK2 (Hexokinase 2) to drive glycolysis, proliferation, migration, and apoptosis resistance via Wnt/β-catenin signaling, particularly under glucose-deprived conditions." (PMID 40917745, 2025). "In summary, these data indicate that targeting HK2 disrupts NLRP12-mediated metabolic reprogramming and malignant progression in gastric cancer." (PMID 40796546, 2025). "Another study revealed that high expression of HMGA1 in gastric cancer patients positively correlates with c-Myc levels and glycolytic markers like GLUT1 and HK2." (PMID 41220952, 2025). "Recent studies have highlighted the roles of key enzymes (e.g., HK2 and PKM2) and signaling pathways (e.g., PI3K/Akt/mTOR, c-Myc, HIF-1α) in gastric cancer metabolism." (PMID 41220952, 2025). "In trastuzumab-resistant gastric cancer cells, PER1 complexes with PPAR-γ to promote upregulation of hexokinase 2 (HK2), thereby enhancing glycolytic activity." (PMID 41451215, 2025). "High expression of HK2 promotes the production and accumulation of lactic acid, resulting in the lactylation of H3K18 in gastric cancer cells." (PMID 40796546, 2025). "QRT‐PCR and western blot results showed that M2‐CM induced the expression of several glycolysis‐related genes including PKM2, GLUTA, HK2, and LDHA in gastric cancer cells." (PMID 38639382, 2024). "QRT‐PCR and western blot results showed that, consistent with M2‐CM, M2‐EX treatment also led to the upregulation of glycolysis‐related genes PKM2, GLUTA, HK2, and LDHA in gastric cancer cells." (PMID 38639382, 2024). "In gastric cancer, WTAP, as an m6A methyltransferase, enhances the stability of HK2 mRNA by binding the 3′-UTR m6A site, thereby promoting the proliferation and glycolysis of gastric cancer." (PMID 39759516, 2024). "RT‐PCR and western blot results showed that, compared to the SI‐NC group, the upregulation of glycolysis‐related genes PKM2, GLUTA, HK2, and LDHA in gastric cancer cells was reversed in the si‐MALAT1 groups." (PMID 38639382, 2024). "In gastric cancer, intraperitoneal seeding is accompanied by enhanced glycolysis mediated by stem cell factor SALL4, which transcriptionally activates HK2 expression." (PMID 38643448, 2024). "We found that in the presence of β‐catenin inhibitor ICG001 and HIF‐1α inhibitor PX‐478, the upregulation of glycolysis‐related genes PKM2, GLUTA, HK2, and LDHA in gastric cancer cells by M2‐EX was greatly attenuated." (PMID 38639382, 2024). "Studies on the mechanisms underlying these phenomena have shown that celastrol inhibits the expression of GLUT1, HK2, and LDH, and reduces the activity of HK and LDH, thereby inhibiting glycolysis in gastric cancer cells." (PMID 36438836, 2022). "Oleanolic acid inhibited gastric cancer glycolysis by down-regulating the expression of HIF-1α, and celastrol inhibited the expression of GLUT1, HK2, and LDH, thereby inhibiting glycolysis in gastric cancer cells." (PMID 36438836, 2022). "Tripartite motif protein 32 (TRIM32), an E3 ubiquitin ligase, promotes glycolysis in gastric cancer cells by targeting GLUT1 and HK2." (PMID 36438836, 2022). "Consistently, expressions of glycolysis key enzymes, GLUT1, hexokinase 2 (HK2), and lactate dehydrogenase-A (LDHA) were significantly upregulated in 5-Fu-resistant gastric cancer cells." (PMID 36447254, 2022). "We found that SALL4 promoted glycolysis by enhancing the expression of HK-2 and interfere with HK-2 expression inhibited the promoting role of SALL4 in gastric cancer cell proliferation, migration and invasion." (PMID 32489324, 2020). "The expression of HK-2 was reported to be elevated in many cancers and was considered a predictive marker of poor prognosis of HCC, breast, and gastric cancer." (PMID 28320429, 2017).
gastric cancer (continued). "Non-flavonoid Phenolic Compounds: Resveratrol, a dietary polyphenol derived from grapes, peanuts, mulberries, and other fruits and vegetables could inhibit the expression of HK2 via the Akt signaling pathway and are effective in NSCLC and gastric cancer." (PMID 36339566, 2022). "Similarly, KLF12 was shown to be upregulated and be a positive regulator of glucose uptake, lactate and ATP production, and hexokinase 2 (HK-2) protein levels in AGS and SNU-638 gastric cancer cell lines." (PMID 36077352, 2022). "In gastric cancer, WTAP enhanced HK2 mRNA stability through m6A modification." (PMID 36207306, 2022). "The mechanism is that through binding the 3’-UTR of HK2, WTAP can enhance the stability of HK2 mRNA, the carcinogenic effect of WTAP and its m6A mediate regulation of Warburg effect in gastric cancer, which provides a new way and target for the treatment of gastric cancer." (PMID 35022030, 2022). "Terpenoids: Oleanolic acid (OA) inhibited tumor growth in human gastric cancer cells (MKN-45 and SGC-7901) by decreasing HK2 and PFK1 expression and intracellular activity, as well as decreasing HIF-1α expression and nuclear abundance, hence reduced glycolysis and induced cell apoptosis." (PMID 36339566, 2022). "The trendency of MET, HK2, and MYC expression in gastric cancer tissues." (PMID 33718248, 2021). "Immunohistochemistry was performed on gastric cancer tissues obtained from 152 patients who underwent curative resection to assess the expression of hypoxia-inducible factor-1α (HIF-1α), glucose transporter-1 (GLUT-1), hexokinase-2 (HK-2) and PDK-1." (PMID 23135628, 2013). "To verify whether the regulation of HK-2 by SALL4 is critical for gastric carcinogenesis, we established subcutaneous tumor-bearing and peritoneal metastasis tumor mouse models by using control and SALL4 knockdown gastric cancer cells." (PMID 32489324, 2020). "However, correlations between the expression of other enzymes, such as HK-2 and PDK-1, and gastric cancer prognosis have not been previously reported." (PMID 23135628, 2013).
cervical carcinoma (59 papers, 2010 to 2025). A carcinoma arising from either the exocervical squamous epithelium or the endocervical glandular epithelium. "In our model, the anti-glycolytic mechanism of GF2 was investigated in human cervical cancer cells in association with miR193a-5p and the β-catenin/c-Myc/Hexokinase 2 (HK2) signaling axis." (PMID 39273365, 2024). "Consistently, in this study, HK2 was also overexpressed in cervical cancer tissues and its high expression was associated with poor OS." (PMID 35184747, 2022). "These include cervical cancer where high HK2 levels are also linked to radiation resistance, in line with the concept that increased glycolysis can confer resistance of cancer cells to radiotherapy." (PMID 29290953, 2017). "Similarly, in the study of locally advanced cervical squamous cell carcinoma, it was found that the high level of HK2 was one of the risk prognostic factors for cervical cancer patients, and associated with the low radiosensitivity." (PMID 36313645, 2022). "In addition, loss of LKB1 in human papillomavirus-positive cervical cancer cells enhanced glycolysis by increasing the expression of HK2 (hexokinase 2), an enzyme that catalyzes the first step of glucose metabolism by phosphorylating glucose to glucose 6-phosphate." (PMID 39544365, 2024). "METTL3 can target the 3’-UTR of HK2 mRNA and recruit YTHDF1 to enhance the stability of HK2, thereby facilitating the Warburg effect in cervical cancer." (PMID 40483535, 2025). "Subsequent Kaplan-Meier survival analysis showed that HK2 expression was negatively correlated with the overall survival probability of patient with cervical carcinoma." (PMID 39713255, 2024). "In contrast, METTL3 boosts cervical cancer cell proliferation by enhancing HK2 stability via YTHDF1 recruitment." (PMID 39219199, 2024). "According to previous studies, HK2 exhibits high expression levels in various malignancies, including breast, liver, colorectal, pancreatic, and cervical cancers." (PMID 38720279, 2024). "Overall, our results provide evidence that GF2 inhibits the Warburg effect via the upregulation of miR139a-5p and the suppression of the Wnt/β-catenin/c-Myc/HK2 signaling axis, making it a potent chemo-preventative candidate for cervical cancer therapy." (PMID 39273365, 2024). "It has been well-documented in scientific literature that HK2, a specific isoform of hexokinase, is substantially overexpressed in cervical cancer tissues." (PMID 39175477, 2024). "It is known that METTL3 targets the 3’-untranslated region (3’-UTR) of HK2 mRNA in cervical cancer cells." (PMID 39175477, 2024). "In the present study, we explore the innovative and rational combination of TCS with benserazide hydrochloride (Benz), a HK2 inhibitor, using HeLa (human cervical cancer) and SCC25 (human oral squamous cell carcinoma) cells as cancer models." (PMID 39713255, 2024). "Compared with adjacent normal tissues, expressions of HK2 mRNA were significantly higher in cervical cancers." (PMID 39713255, 2024). "to upregulate HK2 protein expression through altering YTHDF1/HK2, increasing levels of glycolysis and encouraging the onset and progression of cervical cancer." (PMID 39661501, 2024). "CircCDKN2B-AS1 is upregulated in cervical cancer and precancerous tissues and is positively correlated with HK2 mRNA expression." (PMID 37599427, 2023). "In cervical cancer, the expression level of HK2 (hexokinase 2) is also regulated by the collaborative action of YTHDF1 and METTL3." (PMID 38202722, 2023). "It was showed that increased expression of long non-coding RNA urothelial cancer associated-1 (lncRNA UCA1) by RT enhanced glycolysis by targeting HK2, thereby promoting cervical cancer radioresistance." (PMID 36313645, 2022). "Such a finding supported that HK2-related pathway can serve as a potential target for treating cervical cancer." (PMID 35184747, 2022).